NARF (nuclear prelamin A recognition factor)
Synonyms: IOP2; FLJ10067; DKFZp434G0420
Tractability: PROTAC: ubiquitination databases record sites on it.
Gene: Protein-coding gene on chromosome 17 (82,458,180 to 82,490,537, forward strand). Ensembl gene ENSG00000141562.
Subcellular location: Nucleus
Subcellular location (Human Protein Atlas): Nucleoplasm; Nucleoli
Gene Ontology:
Molecular function: lamin binding
Cellular component: lamin filament; nuclear lumen; nucleolus; nucleoplasm; nuclear lamina; nucleus
Genetic constraint (gnomAD): Loss-of-function variants: 42 observed, 50.25 expected, observed/expected ratio (o/e) 0.84, 90% interval 0.65 to 1.08. The upper end of that interval is the gene's LOEUF score, 1.08, which puts it in group 4 of 6, group 1 being the genes least tolerant of losing a copy. Missense variants: 613 observed, 611.26 expected, observed/expected ratio (o/e) 1, 90% interval 0.94 to 1.07. Synonymous variants: 215 observed, 235.88 expected, observed/expected ratio (o/e) 0.91, 90% interval 0.81 to 1.02.
Homologues: Orthologues: macaque NARF (98% identical), mouse Narf (86% identical), chimpanzee NARF (85% identical), dog NARF (85% identical), guinea pig NARF (83% identical), rat Narf (83% identical), pig NARF (80% identical), rabbit NARF (74% identical), tropical clawed frog narf (61% identical), zebrafish narf (54% identical). Paralogues in human: CIAO3 (48% identical), NDUFS1 (21% identical).
Diseases named in the same sentence as NARF in open-access papers:
NARF is named in the same sentence as 8 diseases in open-access papers, as found by Europe PMC text mining. Sharing a sentence is not in itself a finding about the gene and the disease. The quoted sentences say what the papers report.
multiple sclerosis (2 papers, 2020 to 2022). A progressive autoimmune disorder affecting the central nervous system resulting in demyelination. "Another mutation p.Ser89Leu (RefSeq: NP_036468.1) has been identified in nuclear prelamin A recognition factor (NARF) which has been reported to be associated with mitochondrial dysfunction and iron accumulation in multiple sclerosis." (PMID 32499722, 2020). "The expression level of NARF (nuclear prelamin A recognition factor) in multiple sclerosis (a chronic neuroinflammatory disease) was increased." (PMID 35045818, 2022).
breast carcinoma (1 paper, 2023). "Analysis of human breast cancer biopsy tissues by immunohistochemistry revealed that high NARF protein expression was associated with decreased overall survival of breast cancer patients." (PMID 37768037, 2023). "In 1218 breast cancers (TCGA BRCA dataset), NARF mRNA expression was significantly correlated with a 10-gene HIF signature (R = 0.42; P < .0001) and a 20-gene BCSC signature (R = 0.50; P < .0001)." (PMID 37768037, 2023). "Recent studies have identified HIF-1-dependent expression of PLXNB3, NARF, and TERT in hypoxic breast cancer cells." (PMID 37768037, 2023).
glioblastoma (1 paper, 2022). The most malignant astrocytic tumor (WHO grade IV). "As an E3 ubiquitin ligase, NARF was identified as a positive regulator of cell growth in glioblastoma." (PMID 35300417, 2022).
ileum cancer (1 paper, 2017). "Other protein-encoding genes (FGL2, CTSB, TPP1, SLCO2B1, NARF and JTB) have disease related functions, such as viral hepatitis and ileum cancer." (PMID 28401895, 2017).
tumor (2 papers, 2014 to 2023). "When only 1000 cells were injected (such that BCSCs were limiting), tumors formed in 10/10 mice injected with NTC cells, but only 3/10 and 2/9 mice injected with either of 2 NARF-knockdown subclones, indicating that NARF plays a critical role in BCSC specification and tumor initiation for PLXNB3." (PMID 37768037, 2023).
NARF also shares sentences with these, for which no sentence is quoted: cancer (1 paper); Sepsis (1); viral hepatitis (1).